INS (insulin)
Diseases named in the same sentence as INS in open-access papers (continued):
Sharing a sentence is not in itself a finding about the gene and the disease.
Insulin resistance (continued). "Examination of adipose insulin signaling in fasting animals demonstrated a blunted insulin signaling response to an insulin infusion, consistent with the onset of insulin resistance in the late-fasted seals." (PMID 23997935, 2013). "We specifically focused on the insulin resistance phenotype, the condition of chronic hyperinsulinemia to which cells are exposed in response to low cell sensitivity to insulin activity." (PMID 23497533, 2013). "Insulin resistance induced by palmitic acid also modestly increased Atrogin-1 protein expression, but this increase was reversed by the addition of insulin and PMI5011." (PMID 23437325, 2013). "We had previously shown that 17 weeks of a cafeteria diet led to insulin resistance, high plasma insulin levels, and increased insulin synthesis and secretion in female Wistar rats." (PMID 26904613, 2013). "28-week-old-MSG rats presented an increase in IR/PTP1B interaction and a reduction in insulin signaling in liver, muscle and adipocytes, and a more pronounced insulin resistance." (PMID 23442260, 2013). "This suggests that abnormal p42/p44 MAPK response to insulin in skeletal muscle is a better marker of whole body insulin resistance than the response of the PI3K-PKB pathway, at least in obese non-diabetic individuals." (PMID 23468892, 2013). "If insulin resistance is pronounced, as in type 2 diabetes, even a high level of insulin secretion is insufficient to maintain the plasma glucose concentration within the normal range." (PMID 24188443, 2013). "Ang II promotes insulin resistance and inhibits insulin metabolic signalling by activating mTOR and thus promoting S6K1-mediated IRS-1 serine phosphorylation." (PMID 24400038, 2013). "Insulin resistance describes a physiological condition which is characterized by reduced tissue responses to the action of insulin for any given blood concentration of the hormone." (PMID 23431467, 2013). "Activation of glycogen synthase kinase 3β (GSK-3β) which has a pivotal role in promoting Tau hyper-phosphorylation, is a major consequence of impaired insulin signaling and insulin resistance." (PMID 25035815, 2013). "Severe insulin resistance should be suspected when an individual requires more than 2 units/kg/day of insulin." (PMID 23424687, 2013). "In conditions of insulin resistance hepatic insulin sensitivity and hepatic insulin clearance are decreased proportionally to both hepatic and visceral fat content and this is more evident in patients with Type 2 diabetes compared with non-diabetic subjects." (PMID 23666091, 2013). "MAPK13 null mice exhibit improved glucose tolerance due to enhanced insulin secretion from pancreatic β cells and are protected against high-fat-feeding-induced insulin resistance and oxidative stress-mediated β cell failure." (PMID 23844045, 2013). "Severe insulin resistance should be suspected if an individual has insulin level over 70 μU/mL at fasting or greater than 350 μU/mL post-OGTT." (PMID 23424687, 2013). "To examine which tissues contributed to the insulin resistance, we examined the insulin-stimulated phosphorylation of Akt in the white adipose tissue, gastrocnemius muscle, and liver of wild-type mice fed KD for 6 days." (PMID 23874946, 2013). "Long-term consumption of mate tea significantly increases serum insulin and ameliorates hyperglycemia and insulin resistance in mice." (PMID 23662132, 2013). "In rodents, hepatic AQP9 is repressed transcriptionally by insulin whereas AQP9 increases in states of insulin resistance." (PMID 24205128, 2013). "Insulin resistance is a condition in which normal amounts of insulin fail to elicit a typical insulin response from liver, fat, and muscle cells." (PMID 23840818, 2013). "Thiazolidinediones, which are insulin sensitizers, are widely used in the treatment of type 2 diabetes and have been shown to improve insulin resistance through activation of the PI3K/Akt pathway by initiating IRS signaling." (PMID 24382946, 2013).
Insulin resistance (continued). "Data from animal experiment has found that exposure to hypoxia during pregnancy leads to insulin resistance, impaired glucose homeostasis, and altered expression of genes involved in insulin-signaling pathways in the offspring." (PMID 24455747, 2013). "The results obtained with the multiplex gut hormone panel were reassuring with regard to the roles of insulin resistance and metabolic dysfunction in AD because they reported AD Braak stage declines in insulin and GLP-1, and increases in leptin." (PMID 25035815, 2013). "High plasma levels of insulin and glucose due to insulin resistance are a major component of the metabolic disorder." (PMID 25374688, 2013). "The pathogenesis of GDM is very similar to that of type 2 diabetes (T2D), in which both pancreatic insulin release and chronic insulin resistance have roles." (PMID 23819960, 2013). "Taking together all these considerations, anti-TNF-α therapy exerts beneficial metabolic effects by the reduction of insulin resistance and improvement of insulin sensitivity." (PMID 23431244, 2013). "In the sample as a whole, we observed significant reductions in systolic blood pressure, glucose, insulin, and insulin resistance." (PMID 24369765, 2013). "Insulin resistance is characterised by an impaired response to the actions of insulin, which results in a compensatory increase in insulin (hyperinsulinemia) in an attempt to maintain normal blood glucose levels." (PMID 23658699, 2013). "Given the causative role of inflammation in insulin resistance, we further examined the impact of FSTL1 on insulin signaling in adipocytes." (PMID 24347831, 2013). "Insulin resistance presenting with increased blood glucose level (hyperglycemia) and decreased sensitivity to insulin increases morbidity and mortality in critically ill patients." (PMID 23840093, 2013). "Insulin resistance is associated with the activation of JNK and subsequent JNK-mediated serine phosphorylation of IRS-1 at Ser-307 that negatively regulates the insulin signaling pathway." (PMID 23829668, 2013). "Lipodystrophy is associated with severe metabolic side effects, including dyslipidemia, hepatic insulin resistance, and lipid-driven impaired insulin-stimulated glucose uptake in muscle." (PMID 23533568, 2013). "Triglycerides-increasing alleles of GCKR variants reduce insulin and HOMA-IR index, and protect from insulin resistance in children." (PMID 23383164, 2013). "This is the first report to show direct evidence that insulin resistance is characterized by a higher insulin-stimulated H2O2 generation in skeletal muscle, and NOX2 appears to play an essential role in this mechanism." (PMID 23899788, 2013). "S6K-mediated phosphorylation of IRS1 at Ser636/Ser639 is inhibitory for insulin signaling resulting in insulin resistance." (PMID 28548055, 2013). "Molecular mechanisms involved in the pathophysiology of insulin resistance are related to several alterations in the insulin-signaling cascade." (PMID 23899788, 2013). "Obese patients often develop insulin resistance with various tissues showing low cell sensitivity to insulin activity." (PMID 23497533, 2013). "While the information on the influence of adiponectin in normal insulin sensitivity is unclear, it does, however, appear to augment insulin secretion during insulin resistance." (PMID 23691290, 2013). "Maternal inflammation was also associated with increased maternal insulin resistance, as indicated by increased maternal fasting insulin levels and estimated by the homeostasis model of assessing insulin resistance (HOMA-IR)." (PMID 23825686, 2013). "Impaired insulin action (i.e. insulin resistance, mainly in liver and skeletal muscle) plays a major role in the pathogenesis of type 2 diabetes." (PMID 23894607, 2013).
Insulin resistance (continued). "Multivariable analyses showed that nocturnal hypoxia and not abdominal adiposity was independently associated with hepatic insulin resistance (estimated by HOMA-IR) and global insulin sensitivity (estimated by ISI Matsuda)." (PMID 23951064, 2013). "Obesity and T2DM are multifaceted but characterized by peripheral insulin resistance and compensatory overproduction of insulin by the β cells of the islet leading to increase circulating levels of insulin and enhanced bioavailability of IGF-1." (PMID 23437362, 2013). "Akt -1, -2, -3 are three isoforms of Akt in insulin sensitive tissue, and defective signaling through Akt-2 and -3 mediates insulin resistance in human skeletal muscle." (PMID 24349318, 2013). "This explanation is supported by in vitro models, where FGF-21 is found to protect human myotubes from palmitate-induced insulin resistance, and to increase basal and insulin-stimulated glucose uptake in human myotubes." (PMID 23533568, 2013). "Obesity is important for the development of type-2 diabetes as a result of obesity-induced insulin resistance accompanied by impaired compensation of insulin secretion from pancreatic beta cells." (PMID 23700406, 2013). "Exogenous administration of adiponectin or overexpression in transgenic mice results in improved insulin sensitivity whereas adiponectin deficient mice develop HFD-induced inflammation and insulin resistance." (PMID 23781214, 2013). "Insulin tolerance tests further showed peripheral insulin resistance, with a reduced fold change in insulin secretion observed in isolated islets." (PMID 23826075, 2013). "Supporting this, the transgenic mice in Ortega-Molina’s study showed lower fasting levels of glucose and insulin serum levels and significantly lower value of the insulin resistance index HOMA-IR." (PMID 28548055, 2013). "Studies using cultured cells, animal models, and human subjects demonstrate that ceramide is a key player in the induction of β-cell apoptosis, insulin resistance, and reduction of insulin gene expression." (PMID 23835113, 2013). "Insulin resistance is commonly defined as a decreased response of glucose uptake to the stimulatory effect of insulin." (PMID 23777457, 2013). "Insulin resistance is considered to be responsible for the increase in insulin levels during the compensatory period." (PMID 23483954, 2013). "Insulin resistance leads to hepatocyte steatosis by stimulation of insulin secretion and by increased lipolysis in adipose tissue, which increases circulating fatty acids." (PMID 23653642, 2013). "Serum level of triglycerides shows close parallelism with insulin resistance, serum insulin level and BMI, whereas being inversely correlated with the high density lipoprotein (HDL) level." (PMID 23061769, 2013). "We then analyzed the correlations between serum IGFBP-7 protein levels and other laboratory variables, including fasting glucose, fasting insulin, homeostasis model of assessment insulin resistance (HOMA-IR), IGF-1, and IGFBP-1." (PMID 24180466, 2013). "In T2D pro insulin, insulin ratio increases, that can be the result of insulin resistance or impaired conversion of pro insulin to insulin." (PMID 23870044, 2013). "Irs1−/− mice are known to exhibit postnatal growth retardation and insulin resistance, but a normal glucose tolerance because of the compensatory beta cell hyperplasia despite resistance to the glucose-lowering effect of insulin." (PMID 24284392, 2013). "The percentage of elevated fasting serum insulin in the 3rd tertile of eosinophil percentage was bigger than that in the 1st tertile (22.7% vs.26.6%, P = 0.03), with the percent of insulin resistance the same (22.1% vs.26.5%, P = 0.01)." (PMID 23894289, 2013). "Stress responses in the endoplasmic reticulum (ER) have been associated with increased β-cell apoptosis rates, reduced beta cell mass, lowered insulin production, and increased insulin resistance in type 2 DM patients." (PMID 24348714, 2013).
Insulin resistance (continued). "As is known, individuals with beta-cells unable to sustain increased insulin secretion to compensate for insulin resistance will develop T2DM, and thus inadequate beta-cell function is essential to the course of the disease." (PMID 23349674, 2013). "Increased expression of Enpp1 or its overactivity is correlated with insulin resistance, through direct effects in the insulin signaling pathway." (PMID 23826075, 2013). "Adiponectin levels are positively correlated with insulin sensitivity and negatively with insulin resistance." (PMID 23431295, 2013). "Serum insulin usually reflects the severity of insulin resistance and corresponds to the degree of obesity." (PMID 23826215, 2013). "Later, when beta cell function is impaired and the total insulin secretory capacity falls, hyperglycemia develops because insulin resistance is now accompanied by a relative or absolute insulin deficiency." (PMID 24348462, 2013). "Of note, significant improvements to indices of insulin sensitivity and insulin resistance by the GG homozygotes were identified following a 12 weeks low-fat dietary intervention supplemented with n-3 long chain (LC) PUFA." (PMID 23306188, 2013). "Compensatory hyperinsulinemia due to insulin resistance reflects a combination of increased insulin production and decreased insulin clearance, but most evidence seems to suggest that increased insulin secretion is the predominant factor." (PMID 23983807, 2013). "Obesity, insulin resistance with elevated insulin level, and higher serum concentration of insulin-like growth factor-I are associated with a significantly higher risk of BPH." (PMID 23286275, 2013). "Insulin resistance is a condition whereby the body's cells become resistant to the action of insulin." (PMID 23662132, 2013). "Overall, these data suggest that serum and conditioned medium contain factor/s, which are likely in a larger amount in the insulin resistant than in insulin sensitive subjects, that induce insulin resistance." (PMID 23437106, 2013). "In order to further understand the mechanism by which physical activity protects against aging associated insulin resistance we investigated GLUT4 translocation in myotubes, in the absence or presence of insulin, by immunofluorescence." (PMID 23805253, 2013). "Investigation of the changes that occur in the offspring would highlight the impact of the early nutritional environment on the programming of the insulin signalling pathway ahead of the development of frank insulin resistance and T2DM in later life." (PMID 24386400, 2013). "Pioglitazone treatment significantly reduced the levels of plasma insulin and insulin resistance (19.4±4.0 mU/L and 4.64±0.33, respectively, P<0.05 for both) compared to the level of the fructose-drinking insulin resistance rats." (PMID 23527159, 2013). "Insulin resistance (or low insulin sensitivity) is believed to be a cornerstone of the complications of obesity such as type 2 diabetes and cardiovascular diseases." (PMID 23431266, 2013). "The db/db mouse line is a widely used animal model of T2DM, showing insulin resistance and impaired insulin secretion." (PMID 23349838, 2013). "That inhibition of PP2A resulted in an acute worsening of insulin resistance indicates that PP2A activity is required for insulin-stimulated glycogen storage in vitro and in vivo." (PMID 24150286, 2013). "JZD treatment suppressed the ERS, increased insulin signal transduction, and improved insulin resistance in the rats’ hippocampus." (PMID 23829668, 2013). "IL-10 secreted by M2 macrophages enhances insulin signaling, including that in the liver, thereby having a protective role against obesity-induced insulin resistance." (PMID 23964268, 2013). "Studies have shown that a high fat and high sugar diet can lead to insulin resistance, while defects in the insulin-signaling pathway have been reported with a high fat diet." (PMID 23537367, 2013).
Insulin resistance (continued). "More recently, Li and colleagues reported that ginger extract enhanced insulin release and reduced insulin resistance." (PMID 23662132, 2013). "Glycine’s impact on adiposity and insulin resistance can potentially be explained by improved insulin sensitivity, and/or increased antioxidative and anti-inflammatory capacity." (PMID 24391874, 2013). "Chronic hyperglycemia also leads to glucose toxicity, progressive impairment of insulin secretion and insulin resistance, similar to those observed in diabetic patients, which further worsens the control of blood glucose level." (PMID 23755289, 2013). "The strict link between NAFLD/NASH and insulin resistance is well established and it is highlighted by the implication of insulin signalling in the mechanisms that lead at different levels to the onset and progression of this disease." (PMID 24084730, 2013). "ScN/GFP mice display decreased susceptibility to the development of insulin resistance by HFD as demonstrated by lower fasting glucose and insulin levels and improved glucose tolerance compared to Tie2-GFP mice." (PMID 23840960, 2013). "The euglycemic clamp is the gold standard used to measure insulin resistance in humans, too, but algorithms have been developed that use simple clinical measures to identify insulin resistant humans." (PMID 24348462, 2013). "Insulin resistance leads to a compensatory increase in portal insulin secretion, which suppresses IGFBP-1 concentrations." (PMID 23840881, 2013). "In the broader context of metabolic health, low insulin sensitivity, or insulin resistance, is considered to be an unfavorable condition due to its association with disease risk." (PMID 23298367, 2013). "Previous studies reported that inactivation of Akt can lead to insulin resistance, decreased β cell mass, and impaired insulin secretion." (PMID 24324490, 2013). "For example, gene INS was reported to be involved in insulin resistance, insulin sensitivity and NIDDM." (PMID 24344781, 2013). "Extreme insulin resistance is a condition where an individual insulin requirement is more than 3 units/kg/day." (PMID 23424687, 2013). "For example, a high scale study of adiponectin function in animal models of obesity, insulin resistance, and type 2 diabetes provided strong evidence that adiponectin promotes insulin sensitivity in muscle and in the liver." (PMID 23762871, 2013). "Although the underlying mechanisms are not fully clarified, two relevant factors are represented by the high level of circulating insulin and the biased insulin action in the presence of insulin resistance." (PMID 24115945, 2013). "Since insulin signaling is impaired in type 2 diabetes (patients likely to exhibit insulin resistance) it is possible that the failure of insulin regulatory action contributes to up-regulation of arginase-1." (PMID 24133491, 2013). "Previous studies have shown that chronic activation of intracellular pro-inflammatory pathways within insulin target cells can lead to obesity-related insulin resistance." (PMID 23527073, 2013). "Changes in serum glucose, insulin, adiponectin, homeostasis model assessment of insulin resistance (HOMA-IR) index, and the lipid profile were assessed." (PMID 24106697, 2013). "To harmonize the experimental design in humans and animals, we have thus chosen to demonstrate that the duodenum/jejunum of insulin resistant humans and mice secrete hormone/s inducing insulin resistance." (PMID 23437106, 2013). "Despite the lack of improvement in glucose tolerance, we did observe an improvement in fasting insulin and insulin resistance index in the mice treated with anti-CD40L antibody at the 16 week time point." (PMID 23844072, 2013). "A similar effect was obtained with the human serum from insulin resistant subjects, suggesting that circulating (and thus by definition endocrine) factors are inducing insulin resistance." (PMID 23437106, 2013).